HIF1A (hypoxia inducible factor 1 subunit alpha)
Diseases named in the same sentence as HIF1A in open-access papers (continued):
Sharing a sentence is not in itself a finding about the gene and the disease.
gastric cancer (continued). "Hence, here we review the molecular mechanisms by which HIF-1α signaling stimulates stemness and chemoresistance in gastric cancer, with the clinical efforts and challenges to translate anti-HIF-1α strategies into the clinic." (PMID 36846589, 2023). "HIF-1α is a key inducer of stemness and resistance to systemic therapy in gastric cancer." (PMID 36846589, 2023). "Additionally, FoxO4 also plays a role in inducing downregulation of HIF1α via a VHL protein-independent mechanism, and it has been shown to directly negatively regulate HIF1α in gastric cancer cells, thereby inhibiting various responses to hypoxia." (PMID 37240290, 2023). "Furthermore, apoptosis in response to anticancer therapy and immune attack is attenuated under the influence of HIF-1α, limiting the efficacy of chemotherapeutics, molecularly targeted agents, and immunotherapy in gastric cancer." (PMID 36846589, 2023). "Cumulatively, HIF-1α is instrumental in the adaptation of tumor cells to the demanding tumor microenvironment, influencing proliferation, metastasis, apoptosis, drug resistance, angiogenesis, stemness, and metabolism in gastric cancer." (PMID 38140111, 2023). "Collectively, these new data highlight the importance of HIF-1α in populations at high risk for gastric cancer, but also demonstrate that use of a PHD inhibitor, DMOG, and consequent stabilization of HIF-1α is protective in H. pylori-induced gastric inflammation and injury." (PMID 37828903, 2023). "Therefore, a more exhaustive comprehension of the regulation of HIF-1α in gastric cancer and its role in gastric cancer progression and chemoresistance is required." (PMID 36846589, 2023). "Dznep suppressed the expression of HIF1α in gastric cancer cells." (PMID 37710084, 2023). "Upregulation of HIF-1α stimulates angiogenesis, Warburg effect, epithelial-mesenchymal transition, growth factor signaling, replicative immortality, tumor-promoting inflammation, and stemness in gastric cancer." (PMID 36846589, 2023). "Such efforts may translate efficacious HIF-1α inhibitors into the clinic and uncover new molecular targets in the HIF-1α signaling pathway to increase anticancer efficacy and overcome chemoresistance in gastric cancer treatment." (PMID 36846589, 2023). "However, further efforts are required to unveil the intricate molecular mechanisms by which HIF-1α reprograms gastric cancer cells into stem cells and potentiates chemoresistance." (PMID 36846589, 2023). "When they knocked down the expression of HIF-1α in AGS gastric cancer cell lines, they observed increased sensitivity to 5-fluorouracil (5-FU), a commonly used chemotherapeutic in gastrointestinal cancers, and cisplatin, a widely used potent chemotherapeutic in several cancers." (PMID 36846589, 2023). "Our findings indicate that HIF-1α inhibitors are potent drugs for the treatment of gastric cancer." (PMID 38140111, 2023). "Additionally, we have shown that tipifarnib suppresses HIF-1α expression in gastric cancer cells and inhibits their proliferation and migration in vitro and in vivo." (PMID 37511305, 2023). "Herein, HIF-1α inhibition using siRNA was found to suppress gastric cancer cell growth." (PMID 38140111, 2023). "As hypothesized, HIF-1α inhibition via siRNA led to reduced gastric cancer growth, migration, and invasion, primarily through cell cycle arrest and apoptosis." (PMID 38140111, 2023). "HIF-1α has a substantial impact on intracellular cancer signaling pathways in gastric cancer." (PMID 36846589, 2023). "In addition, overexpression of HIF1α increased viability, invasion, and migration of gastric cancer cells." (PMID 38192437, 2023). "Hence, in vivo findings validated the in vitro findings in gastric cancer cells, strengthening the significance of HIF-1α in gastric cancer." (PMID 36846589, 2023). "Moreover, gastric cancer patients with both HIF-1α- and CD133-positive tumors displayed the poorest prognosis." (PMID 36846589, 2023).
gastric cancer (continued). "Consistent with a previous study, studies showed that the hypoxia-induced factor HIF-1α could facilitate the migration, proliferation, invasion, and tumor angiogenesis of gastric cancer cells." (PMID 37180146, 2023). "Regarding the anti-tumor effects of tipifarnib, we have reported that tipifarnib also exerts anti-tumor effects through the suppression of Rheb farnesylation, leading to the inhibition of the mTOR pathway other than via suppression of HIF-1α in gastric cancer cells." (PMID 37511305, 2023). "Thus, to explore the downstream mechanisms of HIF-1α knockdown in the inhibition of gastric cancer cell growth, we evaluated the expression levels of cell cycle- and apoptosis-related proteins in MKN45 cells." (PMID 38140111, 2023). "It has been demonstrated that PK5 could promote SUMO/ubiquitin-mediated proteasomal degradation of HIF-1α to inhibit VEGF expression in gastric cancer cells under hypoxia." (PMID 36793021, 2023). "The MRHPPGs and HIF-1α expression was significantly elevated in gastric cancer." (PMID 35799793, 2022). "A comprehensive review of the molecular mechanisms by which HIF-1α induces gastric cancer hallmarks could provide a broad perspective to the investigators and reveal missing links to explore in future studies." (PMID 35681691, 2022). "Several studies have investigated how gastric cancer cells are implanted and transferred through milky spots: they provide a hypoxic microenvironment for gastric cancer cells to implant and grow, and HIF-1α in the microenvironment plays a significant role during progression." (PMID 36614904, 2022). "As a result, hypoxia-induced EMT-like CSCs depend on HIF-1α to activate Snail, which may result in recurrence and metastasis of gastric cancer." (PMID 36014432, 2022). "Under hypoxic conditions, HIF-1α promotes exosome discharge in gastric cancer cells and tissues." (PMID 35847022, 2022). "Moreover, hypoxia promotes gastric cancer exosome secretion and increased exosomal miR-301a-3p expression in an HIF-1α-dependent manner, facilitating proliferation, migration, invasion, and EMT." (PMID 36233088, 2022). "OA blocks HIF-1α-mediated glycolysis in gastric cancer cells by inhibiting YAP." (PMID 36438836, 2022). "YAP can control the expression of HIF-1α in gastric cancer cells at the transcriptional level." (PMID 36438836, 2022). "Many studies have suggested that HIF1α plays a key role in the metabolism of gastric cancer." (PMID 35956843, 2022). "To confirm our speculation, we used R scripts and website tools to conduct several bioinformatics analyses to investigate the clinicobiological function of CHAC1, NOX4 and HIF1A and the therapeutic potential of CHAC1, NOX4 and HIF1A in stomach cancer." (PMID 35023280, 2022). "Thus, here we review the impact of HIF-1α on the cancer hallmarks with a specific focus on gastric cancer." (PMID 35681691, 2022). "In gastric cancer cells, HIF1A induces multidrug resistance via miR-27a." (PMID 35659268, 2022). "In addition, PKM2 was reported to promote migration, invasion, and EMT of gastric carcinoma by HIF‐1α/BCL‐6 Pathway." (PMID 34898024, 2022). "In addition, a high level of NEDD4L generally corresponded to a low level of HIF-1α in gastric cancer tissues and led to a favorable prognosis." (PMID 34869021, 2021). "Therefore, there must be other mechanisms to protect HIF-1α from being degraded, thereby continuously promoting gastric cancer angiogenesis and tumor development." (PMID 34671022, 2021). "In line with this, it is reported that ROS upregulated the expression of HIF-1α via activating the NF-κB pathway in gastric cancer cells, which could be attenuated by antioxidants." (PMID 33542787, 2021). "Additionally, it was shown that Piezo1 knockdown in gastric cancer cells significantly reduced HIF-1α expression and metastasis." (PMID 34831037, 2021).
gastric cancer (continued). "For example, the gastric cancer cell proliferation and invasion could be inhibited by 3-deazaneplanocin A through repressing of the HIF-1α and Wnt signaling pathways." (PMID 35355804, 2021). "Collectively, NEDD4L might affect the metastasis of gastric cancer and together with HIF-1α, could predict the prognosis of patients." (PMID 34869021, 2021). "In relation to this, it has been pointed out that CTHRC1 could up-regulate the expression of HIF-1α in gastric cancer." (PMID 34512149, 2021). "Hence, the present study aimed to investigate the effect of AKIP1 on cell invasion and stemness in gastric cancer under hypoxia, and its interaction with hypoxia-inducible factor 1 subunit alpha (HIF-1α) and β-catenin pathways." (PMID 35355804, 2021). "In addition, miR-4646-5p/PHD3/HIF1A signaling can also up-regulate RhoA expression and synergistically promote gastric cancer cell invasion and metastasis." (PMID 33875796, 2021). "As has been reported, HIF-1α knockdown leads to increased ROS production in gastric cancer cells." (PMID 33542787, 2021). "In addition, a study elucidates that the molecule collagen triple helix repeat containing 1 (CTHRC1) enhances the tumor metastasis in animal model of gastric cancer via positively mediating HIF-1α expression." (PMID 35355804, 2021). "Another report indicated that RON/RONΔ160 could form a complex with β-catenin, thus promoting proliferation and migration of gastric cancer cells, which could be further enhanced by hypoxia as well as HIF-1α." (PMID 32310823, 2020). "Crocin was further found to be associated with reduced expression of Krüppel-like factor 5 (KLF5) and hypoxia-inducible factor-1α (HIF-1α), two important transcription factors for the development of gastric cancer, following administration in human gastric cancer cell lines AGS and HGC-27 cells." (PMID 33375488, 2020). "In addition, compound 9 was found to decrease the in vitro AGS gastric cancer cell-induced angiogenesis of HUVECs by blocking hypoxia-inducible factor-1α (HIF-1α) and VEGF expression in AGS cells." (PMID 32751120, 2020). "Moreover, treatment with curcumin, which is known to protect from hypoxia, decreased HIF1α expression in gastric cancer cells, resulting in suppression of BHLHE40 expression." (PMID 32577154, 2020). "Also, the anti-angiogenic role of FOXO1 has been documented in gastric cancer, which when inhibited contributes to tumor growth by upregulating HIF-1α and VEGF." (PMID 32364530, 2020). "Furthermore, compound 9 inhibited the AGS gastric cancer cell-induced angiogenesis of HUVECs by decreasing the expression of hypoxia-inducible factor-1α (HIF-1α) and VEGF." (PMID 32751120, 2020). "Further investigations into the correlation among ROS, HIF-1α, H. pylori infection, and gastric carcinoma could lead to the development of novel strategies for the therapy of H. pylori-associated GC." (PMID 33376580, 2020). "However, HIF-1α overexpression restored the downregulated expression of BCL-6 in gastric carcinoma cells (p < 0.05)." (PMID 33376737, 2020). "Moreover, while HIF-1α expressed mainly in nuclear region, and 66.13% (82/124) of gastric cancer tissues stained positive, and the value was 32% (8/25) in normal tissues (P = 0.001)." (PMID 31673244, 2019). "Our results indicate that the role of HIF-1α in gastric cancer is the opposite of NEDD4L." (PMID 31673244, 2019). "The GCSPC population expanded in primary gastric cancer cells when hypoxia was present in vitro, also hypoxic GCSPCs displayed intensified self-renewal action, but decreased differentiation ability, which was interceded by HIF-1α." (PMID 29867026, 2018). "Serum levels of HIF-1α were also higher in gastric cancer patients than in normal healthy people." (PMID 29899167, 2018).
gastric cancer (continued). "In view of the high incidence of gastric cancer and the functions of hypoxia-inducible factor 1α (HIF-1α), our study aimed to investigate the functionality of HIF-1α in gastric cancer, and to explore the diagnostic and prognostic values of HIF-1α for this disease." (PMID 29899167, 2018). "Serum HIF-1α showed high diagnosic and prognostic values for gastric cancer." (PMID 29899167, 2018). "In addition, serum levels of HIF-1α were also significantly higher in gastric cancer patients than in normal healthy people." (PMID 29899167, 2018). "In addition, treatment with PI3K activator sc3036 significantly reduced the inhibitory effects of HIF-1α siRNA silencing on proliferation, migration, and invasion of gastric cancer cells." (PMID 29899167, 2018). "The results suggest that HIF-1α expression may serve as a prognostic marker for patients with gastric cancer." (PMID 29899167, 2018). "Up-regulated expression of HIF-1α has also been observed in gastric cancer." (PMID 29899167, 2018). "In gastric cancer, GAPLINC is directly activated by HIF-1α and its overexpression is associated with poor prognosis and could promote tumor migration and invasive behavior." (PMID 28789687, 2017). "Indeed, PVT1 bound miR-186 and induced upregulation of HIF-1α (Hypoxia-inducible factor 1-alpha subunit), a target of miR-186 which was related to poor prognosis and invasiveness in gastric cancer." (PMID 29147648, 2017). "It was previously reported that HIF-1α has a carcinogenic role in gastric cancer." (PMID 29108235, 2017). "Although HIF-1α reportedly is pro-carcinogenic, it was found here to promote cell cycle arrest, which may potentially be relevant in early steps of gastric cancer development." (PMID 28401064, 2017). "This study was designed to answer the question whether the tumor suppressor SIRT3 protein influences ROS production and HIF-1α activity in H. pylori-infected gastric cancer cells." (PMID 29108235, 2017). "Metformin may inhibit gastric cancer development and progression by inhibiting HIF1α/PKM2 signaling." (PMID 28903449, 2017). "There is evidence that gastric epithelial ROS may lead to HIF-1α expression under normal oxygen conditions and facilitate the tumor angiogenesis of gastric cancer." (PMID 29295534, 2017). "Previous data also showed that FAK-PI3K and p42/44MAPK(ERK1/2) might be the major signaling molecules in MGr1-Ag/37LRP induced HIF-1α expression and activity which contributed to drug resistance and apoptosis resistance in gastric cancer cell lines." (PMID 29069734, 2017). "The results demonstrate that the miR-186/HIF-1α axis has an antioncogenic role in gastric cancer." (PMID 27159677, 2016). "A similar upregulation of HIF-1α is also seen in gastric cancer." (PMID 27023622, 2016). "CCL2 expression also correlates closely with HIF-1α expression in gastric cancer." (PMID 27271610, 2016). "Therefore, in our study, we investigated the roles of HIF-1α induced miR-421 in gastric cancer, and we found that miR-421 promoted metastasis, inhibited apoptosis, and induced cisplatin resistance by targeting E-cadherin and caspase-3." (PMID 27016414, 2016). "Since HIF-1α gene has been reported as a transcriptional target of NF-κB, we performed EMSA to evaluate the autophagy defect mediated transcriptional activity of NF-κB in gastric cancer cells using nuclear extracts and specific probe (containing NF-κB binding site in HIF-1α promoter)." (PMID 26497999, 2015). "Altogether, these experiments demonstrated that compromised autophagy could enhance the EMT phenotype of gastric cancer cells and this process could be HIF-1α-dependent." (PMID 26497999, 2015). "In conclusion, HIF-1α inhibition combined with GI treatment may be a promising target for the hypoxic region in gastric cancer, where conventional chemotherapy often fails." (PMID 26339797, 2015).
gastric cancer (continued). "This study also displayed that autophagy defect could induce EMT of gastric cancer cells through up-regulation of HIF-1α expression, in agreement with previous study that EMT regulators are located downstream of HIF-1α." (PMID 26497999, 2015). "Hypoxia induced cell death was also confirmed in other HIF-1α knockdown gastric cancer cells 74-KD." (PMID 26339797, 2015). "In addition, we examined the relationship between CD133 expression and HIF-1α expression using immunohistological staining of gastric cancer tissue specimens." (PMID 23558457, 2014). "However, though researched for years, the prognostic role of HIF-1α in gastric cancer is still controversial." (PMID 24614305, 2014). "HIF-1α overexpression could be considered a useful independent prognostic biomarker in gastric cancer after gastrectomy, and is correlated to both a poor overall survival and disease-free survival in these patients." (PMID 24614305, 2014). "Furthermore, the GCSPC population expanded in primary gastric cancer cells under hypoxic condition in vitro, and hypoxic GCSPCs showed enhanced self-renewal ability, but reduced differentiation capacity, mediated by HIF-1α." (PMID 25142304, 2014). "Hence, the current study is the single largest sample size in which correlation of HIF-1α and prognosis of gastric cancer was evaluated." (PMID 24614305, 2014). "However, though researched for years, the prognostic role of hypoxia-inducible factor 1 alpha (HIF-1α) in gastric cancer is still controversial." (PMID 24614305, 2014). "Our work here suggests that overexpression of HIF-1α could be an important indicator of poor prognosis in gastric cancer after gastrectomy." (PMID 24614305, 2014). "Meta-analyses of HIF-1α/PTEN/CD44v6/Survivin expressions on gastric cancer." (PMID 24647137, 2014). "Patients with T3 and T4 gastric cancer had higher HIF-1α expression in 9 studies (1188 patients; OR = 3.050, 95% CI = 2.067–4.501, P<0.001) than those with T1 and T2 gastric cancer, with moderate between-study heterogeneity (I2 = 53.8%, subgroup difference P = 0.027)." (PMID 24647137, 2014). "We have previously reported that HIF-1α expression is a poor prognostic factor in gastric cancer." (PMID 23558457, 2014). "Despite the clinical development of anti-HIF-1α therapies, the prognostic and clinical value of HIF-1α overexpression in gastric cancer cells remains unclear." (PMID 24647137, 2014). "If this is the case, then inhibiting HIF-1α expression may lead to improved prognosis in gastric cancer." (PMID 23558457, 2014). "The association of the clinical value of DEC1 expression and HIF-1α, the endogenous marker of hypoxia, has not been reported for gastric cancer." (PMID 23445622, 2013). "Few reports have thus far studied the carcinogenic role of HIF-1α in gastric cancer." (PMID 24216696, 2013). "HIF-1α is known to transcriptionally upregulate the VEGF expression in gastric cancer." (PMID 24216696, 2013). "As Zhou and Li described, the expression of RhoE is increased in gastric cancer by the induction of HIF-1α, and whose expression could go augmented still more when cancer cells generate resistance to anti-tumor drugs." (PMID 24312338, 2013). "These two reports strongly indicate that the treatment using siRNA against HIF-1α might be an effective therapy, via increasing 5FU sensitivity in gastric cancer patients." (PMID 24216696, 2013). "In our study, we presented a strongly positive correlation between Tregs number and HIF-1α expression, suggesting that hypoxia may contribute to Tregs infiltration in gastric cancer." (PMID 23723999, 2013). "Thus, we aimed to verify the relationship between HIF-1α expression and that of other enzymes involved in gastric cancer." (PMID 23135628, 2013). "Further investigation is needed to confirm these results, but metabolic alternation through HIF1α induction in tumor hypoxia could increase FDG uptake in gastric cancer." (PMID 23718763, 2013).